IL6 (interleukin 6)
Diseases named in the same sentence as IL6 in open-access papers (continued):
Sharing a sentence is not in itself a finding about the gene and the disease.
Obesity (continued). "This miRNA has not been previously reported as associated with obesity, however among its targets are those involved in the pathogenesis of obesity-related complications, e.g., genes encoding interleukins (IL-6, IL-17B and IL-22), apolipoproteins (APOA5) and their receptors (APOBR)." (PMID 29280944, 2017). "Data suggest that decreased serum level of IL-6 following antipsychotic therapy could be predisposing factor for the development of obesity and obesity-related metabolic disorders in schizophrenia." (PMID 29163240, 2017). "In addition, hepatic stellate cells were reported to exhibit senescence-associated secretory phenotype in mice with obesity, secreting various inflammatory and tumor-promoting factors in the liver, including IL-1β, IL-6 and CXCL1." (PMID 28458256, 2017). "Finally, IL-6 is likely the cytokine most implicated in obesity-related NAFLD development and progression." (PMID 28360082, 2017). "Obesity in IL-6-deficient mice was partly reversed by long-term IL-6 replacement." (PMID 29062839, 2017). "IL-6 may be associated with a chronic, low-grade inflammatory state, which is generally associated with obesity." (PMID 28654680, 2017). "Secondly, increased concentration of the pro-inflammatory cytokines such as TNF-α and IL-6 associated with obesity and diabetes might impair insulin action by suppressing insulin signal transduction." (PMID 27581604, 2016). "Obesity presents a chronic, low grade vascular inflammation, caused by macrophage infiltration, increased level of proinflammatory adipokines (leptin, resistin) and cytokines levels (IL-6, TNF alpha), and reduced levels of protective adiponectin." (PMID 27092288, 2016). "In addition, studies evaluating the chronic inflammation associated with obesity and increased risk of metabolic syndrome have suggested that IL-6 is an important cytokine released by adipose tissue macrophages." (PMID 27287704, 2016). "Indeed, IL-6 overexpression contributes in maintaining the anti-inflammatory macrophage population in adipose tissue that would limit the development of obesity-associated IR." (PMID 27111539, 2016). "The finding that CRP was significantly associated with an increased risk of CVD and decreased the BMI-associated CVD risk substantially, could imply that interleukin-6-related pathways may play a role in mediating overweight- and obesity-related CVD." (PMID 26035431, 2015). "Administration of IL-6 has been reported to confer protection against steatosis, but plasma and tissue IL-6 concentrations are elevated in chronic liver diseases, including fatty liver diseases associated with obesity and alcoholic ingestion." (PMID 26035386, 2015). "Moreover, obesity is associated with increased production of proinflammatory adipokines, including monocyte chemoattractant protein-1, interleukin-6 (IL-6), and tumor necrosis factor-α (TNF-α)." (PMID 25785277, 2015). "Moreover, IL-6 induces the polarization of tumor-associated macrophages, which are similar to obesity-associated M2 macrophages." (PMID 26294848, 2015). "Indeed, both obesity and aging are associated with pro-inflammatory states where high levels of C-reactive protein, IL-6 and TNF were found in the blood." (PMID 26604973, 2015). "The justification for thisphenomenon is that the increase of the release of free fatty acids, resistin, IL-6 andTNF-alpha by the adipose tissue and the reduction of the release of adiponectincontribute to the development of insulin resistance in obesity and increased risk ofdeveloping NAFLD6." (PMID 26734800, 2015). "Overall, the role of IL-6 in insulin sensitivity and glucose homeostasis remains controversial; and we speculate that the obesity-associated perturbations in IL-6 and its receptor likely have diverse effects in different tissues and organs." (PMID 26200663, 2015).
Obesity (continued). "In addition to the storage of lipids in the adipose tissue, adipocytokines like adiponectin, leptin, TNF, IL-6, resistin play an important role in tissue physiology and have been shown to be linked to obesity, insulin resistance and β-cell dysfunction." (PMID 28702225, 2015). "The role of IL-6 in obesity-associated chronic low-grade metabolic inflammation is controversial." (PMID 26200663, 2015). "Contrary to these reports, IL-6−/− mice develop a mature onset obesity that can in part be reversed by replacing IL-6, suggesting an important therapeutic window for IL-6 levels that may be beneficial compared to levels linked with disease." (PMID 24465369, 2014). "Furthermore, adiposity, especially in the context of obesity and metabolic syndrome, is associated with high levels of IL-6 and TNF-α." (PMID 25338520, 2014). "Thirdly, due to the production of inflammatory cytokines such as interleukin-6 tumor necrosis factor-alpha and platelet activating factor from adipose tissues, obesity is considered as one of the major risk factor for cardiovascular events such as in-stent re-stenosis." (PMID 24580749, 2014). "Saturated fatty acids from obesity-induced lipolysis are capable of activating macrophages and thereby activating NF-κB signaling, which in turn leads to transcriptional activation of genes encoding pro-inflammatory factors including IL-1β and IL-6." (PMID 25515685, 2014). "It has been hypothesized that dysregulated production of adipocytokines (PAI-1, leptin, resistin, visfatin, adiponectin) and cytokines (TNF-α and IL-6) from accumulated fat participates in the pathogenesis of obesity-associated MS." (PMID 25548896, 2014). "hsCRP is more sensitive marker associated with obesity than IL-6 and TNF-α." (PMID 24507240, 2014). "T2D and obesity have been associated with a genetic polymorphism of IL-6 (−174 G/C), supporting that level of expression of this molecule may influence metabolic homeostasis." (PMID 25140176, 2014). "Obesity is associated with migration of bone marrow-derived macrophages into the visceral adipose tissue where they acquire an M1 (classical activation) phenotype and secrete proinflammatory cytokines such as IL-1, IL-6, and TNF-α." (PMID 24823865, 2014). "Adipocytokines such as TNFα, IL-6, adiponectin, leptin, visfatin, and resistin are cytokines secreted primarily by visceral adipose tissue and are thought to be involved in the positive correlation between obesity and the increased risk of gastric cancer." (PMID 24929539, 2014). "Plasma IL-6 levels increase during IR associated with obesity and diabetes; therefore, IL-6 plasma concentration may represent an independent predictor of risk for T2DM." (PMID 24926351, 2014). "Interestingly, various hormones associated with insulin resistance and obesity including catecholamines, insulin, glucocorticoids, TNFα and IL-6 down-regulate adiponectin expression and secretion in fat cells in vitro." (PMID 24968098, 2014). "Expanded adipose tissue releases pro-inflammatory cytokines, such as tumor TNF-α, NFκB and IL-6, which may play an important role in obesity-associated hepatocarcinogenesis." (PMID 25533006, 2014). "However, LMW adiponectin has been associated with decreased IL-6, and negatively correlated with waist circumference, meaning that its increased concentrations are inversely related to adiposity and obesity." (PMID 24740401, 2014). "In addition, there is a growing body of evidence linking polymorphisms within the IL-6 gene to increased risk of obesity and dyslipidaemia." (PMID 24962479, 2014). "The chronic inflammatory response caused by obesity and enhanced production of IL-6 and TNFα may also increase the risk of many cancers." (PMID 25258478, 2014).
Obesity (continued). "Specifically, we suggest that elevated levels of tumor necrosis factor-α (TNF-α) or interleukin 6 (IL-6)—both adipokines and known risk factors for destructive periodontal disease—in obesity and metabolic syndrome contribute to the onset and development of destructive periodontal disease." (PMID 24068858, 2013). "Of note, CRP seems to be more strongly associated with obesity than IL-6." (PMID 23781331, 2013). "Moreover, we show that 1,25(OH)2D3 also inhibits adipocyte production of the major cytokines IL-1β and IL-6, both of which are critically involved in obesity associated inflammation and insulin resistance." (PMID 23637889, 2013). "Additionally, obesity is associated with low-grade inflammation and slightly elevated levels of cytokines such as IL-6, IL-8, and TNF-α in body fluids and tissues." (PMID 23936654, 2013). "Obesity is associated with a state of chronic or low grade systemic inflammation which increases production of obesity-related inflammatory cytokines, such as IL-1β, IL-6, TNFα, leptin and decrease anti-inflammatory cytokine levels, such as adiponectin." (PMID 24143244, 2013). "In addition, adipose tissue, including that of the fat pad in the knee, is an important source of inflammatory mediators, including IL-6, at least partly explaining the association of OA with obesity." (PMID 23206933, 2012). "In addition, it suggests that increased secretion of IL-6 characterizes different types of adipose tissue metabolic stress, i.e. diet induced obesity and CAV1 deficiency." (PMID 23049990, 2012). "Although obesity is associated with a low-grade, chronic inflammation in the adipose tissue, DD adipose tissue exhibits increased expression of IL-6 mRNA and evidence of pro-inflammatory macrophages, even in comparison to BMI- and weight-matched obese controls." (PMID 22300160, 2012). "To further investigate the status of IL-6 signaling in skeletal muscle in obesity-associated type 2 diabetes, we isolated satellite cells from skeletal muscle of people that were healthy (He), obese (Ob) or were obese and had type 2 diabetes (DM), and differentiated them in vitro into myocytes." (PMID 22761857, 2012). "We recently demonstrated that sustained elevation of IL-6 in obese mice receiving IL-12+ IL-18 contributes to the delayed resolution of AP in obesity and is associated with increased production of osteopontin and tissue inhibitor of metalloproteinase-1 (TIMP-1)." (PMID 22815875, 2012). "We hypothesized that skeletal muscle in obesity-associated type 2 diabetes develops a resistance to IL-6." (PMID 22761857, 2012). "Chronic elevation of systemic IL6 in humans is associated with type 2 diabetes, obesity, and sedentary lifestyle and may be attributable to increased number of macrophages residing in the adipose tissue." (PMID 22474579, 2012). "Thus, it has been suggested that IL-6 contributes to obesity-associated insulin resistance, supported by the findings that increased plasma levels of IL-6 are associated with both obesity and insulin resistance." (PMID 22761857, 2012). "This important finding suggests that the increased IL-6 production associated with obesity and insulin resistance may in fact represent a mechanism for increasing the production of insulin, an idea that warrant further investigation." (PMID 22761857, 2012). "Variants in or near LEP, POMC, MC4R, and IL-6 genes confer a significant risk to human obesity." (PMID 21390334, 2011). "Finally, we were surprised that the FTO A-allele tended to lower IL-6 levels, since we would have expected obesity to lead to increased IL-6 levels." (PMID 21246032, 2011). "IL-6 levels positively correlate with higher all-cause mortality, unstable angina, left ventricular dysfunction, propensity to diabetes and its complications, hypertension, obesity and several types of cancer." (PMID 20937099, 2010).
Obesity (continued). "A variety of adipocyte-derived biologically active molecules have been identified, including leptin, resistin, TNF-α, and IL-6, that may contribute to obesity-linked metabolic abnormalities." (PMID 19254366, 2009). "Additionally, in obesity, serum IL-6 levels are positively correlated with extent of obesity and risk for subsequent development of overt diabetes." (PMID 19936194, 2008). "Increased serum concentrations of TNF, NO,and IL-6 are strongly associated with obesity, and proinflammatory cytokines sourced from adipose tissueincluding TNF, and IL-6 are among several important factors that participate inthe development of insulin resistance and type 2 diabetes mellitus." (PMID 18309368, 2008). "Increased blood concentrations of TNF-α and IL-6 were associated with obesity and type II diabetes." (PMID 15904534, 2005). "The increased concentrations of TNF-α and IL-6, associated with obesity and type 2 diabetes, might interfere with insulin action by suppressing insulin signal transduction, which in turn might promote inflammation." (PMID 15904534, 2005). "Indeed, obesity is associated with elevated levels of cytokines whose systemic administration leads to impaired glucose homeostasis, such as TNFα and IL-6, which we show here to mediate the inflammatory induction of human resistin." (PMID 15578112, 2004). "The main mechanisms involved in obesity-related vitamin D deficiency include decreased bioavailability due to its accumulation in adipose tissue, reduced intestinal absorption, impaired metabolism, decreased liver 25(OH)D synthesis, and the influence of leptin and IL-6 on hepatic VDRs." (PMID 40724644, 2025). "In addition, there is evidence suggesting that obesity is associated with lymph node metastases after RP, owing to the deranged prostatic microenvironment and cellular DNA caused by inflammatory factors (IL-6, IL-8, VEGF, leptin) and altered insulin-IGF-1 axis." (PMID 40364176, 2025). "However, whether these transient spikes of IL-6 are enough to counteract obesity- or T2D-associated chronic inflammatory signals remain elusive." (PMID 41277875, 2025). "As proinflammatory cytokines have been linked to obesity-related insulin resistance and the activation of adipokines, another possible theory behind JAKi-associated weight loss is that reduced levels of IL-6 via JAK inhibition might lead to decreased adiposity." (PMID 39872731, 2025). "In addition, given that circulating levels of IL-6 or BCAAs are associated with obesity and diabetes, IL-6–mediated BCAA metabolism in skeletal muscle and BAT may also be associated with muscle atrophy in metabolic diseases." (PMID 41143503, 2025). "Obesity is associated with chronic low-grade inflammation, which can promote carcinogenesis as excess adipose tissue leads to the secretion of inflammation-related macrophages and adipokines such as interleukin (IL)-6, plasminogen activator inhibitor-1 (PAI-1), and C-reactive protein (CRP)." (PMID 40722646, 2025). "Obesity and overweight may worsen RA symptoms and outcomes due to increased inflammation caused by pro-inflammatory cytokines secreted by adipose tissue (e.g., IL-6 and TNF-α)." (PMID 40597453, 2025). "Of note, it is essential to highlight that the use of cytokines as biomarkers of MASLD may face some critical challenges in the clinical context: (a) many cytokines implicated in MASLD, such as IL-1β, TNF-α, and IL-6, are also involved in obesity, IR, and T2DM, which usually coexist with MASLD." (PMID 40794228, 2025). "The clinical study conducted by Di Renzo and colleagues identified new indices and predictive parameters based on body composition and IL-6 gene polymorphism (rs1800795) that could distinguish individuals with lipedema from those with normal weight-obesity (NWO) and obesity." (PMID 38958868, 2024).
Obesity (continued). "Inflammation associated with obesity is primarily caused by excess nutrients that activate the signaling pathways localized in adipose tissue triggering inflammatory responses resulting in the increased secretion of cytokines such as IL-6, TNF-α, IL-17, and IL-23; c-JNK; and NF-κB." (PMID 39845239, 2024). "Furthermore, the low-grade systemic inflammation caused by some molecules such as interleukin-6 (IL-6), IL-1β, TNFα, leptin, and adiponectin may play a role in obesity association with KOA." (PMID 39472918, 2024). "IL-6 leads to an increased risk of inflammation, which may cause brown fat cells to dysfunction and render them unable to break down fat properly, resulting in the development of obesity." (PMID 38590820, 2024). "In a mouse model of obesity associated with breast cancer, administration of fish oil in addition to a high-fat diet decreased the levels of inflammatory cytokines tumor necrosis factor-α and interleukin (IL)-6 and increased the levels of the anti-inflammatory cytokine IL-1026." (PMID 38228757, 2024). "High saturated fat intake was associated with increased IL-6 levels (odds ratio = 2.03, 95% confidence interval [CI] = 1.00–4.11, p < 0.047), whereas high total fat intake elevated leptin levels by 2.14-fold (95% CI = 1.12–4.10, p < 0.021) in participants with obesity." (PMID 39700087, 2024). "In addition to the stimulation of IL-6 synthesis, targeting the downstream IL-6 signaling pathway may also be a straightforward approach to increase weight loss in obesity." (PMID 38474057, 2024). "Additionally, IL-6 has been implicated in the regulation of appetite and energy balance: elevated IL-6 production may contribute to low-grade systemic inflammation associated with obesity, a state often referred to as meta-inflammation." (PMID 38921006, 2024). "The excess visceral adiposity, typical of obesity, is responsible for increasing the number of molecules that induce cancer pathogenesis, such as leptin, resistin, and other adipokines, in addition to pro-inflammatory cytokines such as IL-1, IL-6, IL -8, and TNF-α, elevating the risk of neoplasms." (PMID 39042663, 2024). "CRP, which is generated by liver cells in response to an increase in IL-6 production by macrophages and adipocytes, is a sensitive marker for systemic inflammation and is implicated in the etiology of numerous chronic disorders, such as obesity and coronary heart disease." (PMID 37734921, 2023). "Similarly, the downregulation of IL-6 mRNA levels suggests that CGWE may ameliorate the inflammatory state associated with obesity, potentially leading to improved metabolic outcomes." (PMID 37571229, 2023). "Increased BMI and obesity are strongly associated with changes in the physiological function of adipose tissue, leading to enhanced secretion of adipocytokines and inflammatory factors including leptin, interleukin-6 (IL-6), tumor necrosis factor-α (TNF-α), MCP-1, resistin, and hs-CRP." (PMID 37147659, 2023). "Moreover, IL-6-deficient mice showed variable obesity phenotypes between studies, which might be partially correlated with the complex etiology of obesity." (PMID 37187893, 2023). "Interestingly, we frequently observed that many circRNAs were involved in regulating Il6 expression in astrocytes exposed to TNF-α and Chol, indicating that obesity-linked circRNAs may be key factors that regulate the IL-6 cytokine production in astrocytes." (PMID 37047207, 2023). "Furthermore, Th1 polarization correlated with leptin, an adipokine associated with obesity-mediated inflammation, and IL-6, a cytokine downstream in the leptin inflammatory pathway, suggesting that obesity was driving the Th1 systemic inflammation in obese children with asthma." (PMID 38292857, 2023). "Obesity/insulin-resistance may be the main cause of sleep apnea, which in turn may accelerate these metabolic abnormalities because of the gradual rise of cytokines, such as IL-6 and TNF-α." (PMID 37215125, 2023).